NAT10 (N-acetyltransferase 10)
Diseases named in the same sentence as NAT10 in open-access papers (continued):
Sharing a sentence is not in itself a finding about the gene and the disease.
tumor (continued). "Our results suggest that NAT10 regulates anoikis resistance in HCC cells by modulating key genes, including SMAD3, thus facilitating tumor cell EMT and enhancing malignant progression." (PMID 41476650, 2025). "Therefore, future studies on a larger and more comprehensively annotated patient cohort are crucial to validate our findings and determine whether NAT10 expression correlates with specific clinical pathological features (e.g., tumor grade, stage, or molecular subtype)." (PMID 41189569, 2025). "NAT10-mediated ac4C acetylation of KRT8 mRNA stabilizes its expression, contributing to tumor growth, migration, and invasion." (PMID 41203621, 2025). "Elevated NAT10 expression stabilizes SMAD3 mRNA via this modification, facilitating tumor progression and contributing to the activation of the TGF‐β signaling pathway." (PMID 41476650, 2025). "Specifically, NAT10 enhances the stability of ETS2 and KRT8 mRNA via ac4C modification, thereby promoting tumor malignancy and immunosuppression." (PMID 41203621, 2025). "The NAT10‒ACOT7 axis orchestrates fatty acid metabolism to suppress ferroptosis, thereby promoting tumor progression." (PMID 41316475, 2025). "In conclusion, this study established NAT10 as a central regulator of PC progression and immune evasion through the ac4C-dependent stabilization of ETS2 and KRT8 mRNA, thereby promoting tumor immunosuppression and malignancy." (PMID 41203621, 2025). "The poorly characterized RNA helicase domain of NAT10 is critical for cell growth in vitro, while both RNA helicase and NAT domains are essential for primary tumor growth and brain metastasis in vivo." (PMID 40138393, 2025). "NAT10 KD significantly impaired the PNI process, indicating a decreased tumor infiltration into the endoneurium and perineurium of the nerve." (PMID 40119353, 2025). "The half maximal inhibitory concentration (IC50) values revealed a selective effect of NAT10‐2023 on cancer cell viability, with significantly lower IC50 values for SK‐HEP‐1 and HCCLM3 compared to LX2 and HEK293, suggesting a strong tumor‐targeting capability." (PMID 41476650, 2025). "Genetic or pharmacological inhibition of NAT10 with Remodelin attenuated VEGFA secretion, enhanced pericyte coverage and basement membrane integrity, and normalized tumor vasculature in syngeneic GC models." (PMID 40860183, 2025). "Compared with NAT10-KD cells, the invasion of tumor cells toward DRG and tumor proliferation were significantly increased when ITGB5 was overexpressed." (PMID 40119353, 2025). "Remodelin has been shown to directly inhibit NAT10 expression in HNSCC cell lines, decrease MYC expression, and upregulate LDHA expression to promote tumor spread." (PMID 39764566, 2025). "U14 cellstreated with NAT10 KD and anti-PD-L1 or NP1192 alonealso presented CD8+ T-cell-mediated tumor cell killingefficacy." (PMID 41341045, 2025). "NAT10/ac4C-YTHDC1/m6A axis boosts glycolysis via enhanced enzyme translation, promoting tumor progression." (PMID 41446042, 2025). "However, several questions warrant further investigation, such as the impact of microbiota metabolism on ac4C epigenetic modification, the specific effects of NAT10 on the tumor immune microenvironment, and whether deacetylases exist to counteract NAT10-driven oncogenesis." (PMID 40881352, 2025). "NAT10 remodeled the ac4C modification of the mRNAs of the oncogenic genes ATAD2, SOX4, and SNX5, which have been confirmed to play important roles in tumor metastasis and angiogenesis." (PMID 40301349, 2025). "Huh6 cells were subcutaneously transplanted into nude mice, which were monitored weekly for tumor size while receiving treatments with the YAP1 inhibitor Verteporfin, the NAT10 inhibitor Remodelin, and the G6PD inhibitor Fluasterone." (PMID 40303290, 2025).
tumor (continued). "ERRFI1, as a feedback suppressor of EGFR and ERBB2, is regulated by NAT10 in an ac4C-dependent manner, participates in the EGFR-mediated signaling pathway, and participates in tumor development and chemotherapy resistance in CRC." (PMID 41316475, 2025). "In vivo experiments involving the subcutaneous implantation of sh-Control, sh-NAT10, and sh-IGF2BP2 CAL27 cells in nude mice demonstrated a significant decrease in tumor size with the interference of NAT10 and IGF2BP2 (p < 0.001)." (PMID 40597017, 2025). "Here, a novel role of NAT10 in inducing lysosomal acidification is revealed, and the clinical and biological significance of ATP6V0E1 in tumor metastasis is uncovered." (PMID 40729677, 2025). "Future research will further elucidate the specific mechanisms of NAT10 in EMT and cancer metastasis and explore its potential as a therapeutic target to curb tumor spread and metastasis." (PMID 39764566, 2025). "NAT10 interacts with its 3’-UTR to enhance ac4C/stability, activates the Wnt/β-catenin pathway, and promotes tumor progression." (PMID 41446042, 2025). "Mechanistic studies suggest that NAT10 regulates tRNA abundance in an ac4C RNA‐dependent manner, promoting EGFR protein translation efficiency and facilitating ESCA tumor malignancy." (PMID 39764566, 2025). "Similarly, in clear-cell renal cell carcinoma (ccRCC), NAT10 acts through ankyrin repeat and zinc finger peptidyl tRNA hydrolase 1 (ANKZF1) to increase the nuclear localization of yes1-associated transcriptional regulator (YAP1), thereby driving tumor progression and lymphangiogenesis." (PMID 41316475, 2025). "By Day 6, NAT10 KD in PANC-1 and MIA PaCa-2 cells had significantly reduced tumor cells invasion towards the DRG." (PMID 40119353, 2025). "Additional researches indicate that knockdown of METTL14, NAT10, and NSUN2 in OS cell lines significantly inhibits tumor growth in nude mice 11-13." (PMID 39897026, 2025). "Here, we provide evidence that NAT10 promotes the expression of ITGB5, a vital receptor in the focal adhesion pathway, thereby activating this signaling pathway to promote tumor invasion." (PMID 40119353, 2025). "In conclusion, our results revealed that circMAST1 inhibited NAT10 from binding to YAP mRNA and decreased YAP mRNA ac4C modification to promote its degradation and inhibit tumor growth and metastasis in CCa." (PMID 38331765, 2024). "NAT10 mediates the ac4C modification of ferroptosis suppressor protein 1 mRNA, thereby inhibiting ferroptosis of CRC cells, facilitating tumor progression." (PMID 39640362, 2024). "We postulated that NAT10 regulates the progression of EMT, which has been widely acknowledged as a crucial process in tumor migration." (PMID 38922788, 2024). "ELISA and flow cytometry confirmed that NAT10 knockdown significantly increased CCL25 levels, promoting CD8+ T cell recruitment and enhanced cytotoxicity in the tumor microenvironment." (PMID 39648231, 2024). "NAT10 has the ability to advance the cell cycle and the epithelial‐mesenchymal transition (EMT), both of which raise the malignancy of tumor cells." (PMID 38922788, 2024). "We also confirmed that circMAST1 sequestered NAT10 and inhibited NAT10-mediated ac4C modification of YAP mRNA, reducing YAP mRNA stability and suppressing tumor growth and metastasis." (PMID 38331765, 2024). "Our results also revealed that tumor cells express CCR9, with CCR9 levels significantly upregulated following NAT10 knockdown." (PMID 39648231, 2024). "Flow cytometry showed an inverse correlation between NAT10 expression and CD8+ T cell infiltration in xenograft tumor model, consistent with public database analyses." (PMID 39648231, 2024). "By regulating EMT pathway markers and suppressing CD8+ T cell recruitment and cytotoxic activity, NAT10 fosters an immunosuppressive TME, thereby accelerating tumor progression." (PMID 39648231, 2024).
tumor (continued). "Collectively, the results confirmed the presence of ac4C modification on NOTCH3 mRNA molecules at the single‐base level, uncovering a signaling cascade involving NAT10 (K823 Khib) and NOTCH3 (ac4C), which regulates fibronectin during tumor metastasis." (PMID 39640362, 2024). "In BLCA, NAT10 overexpression acetylates BCL9L, SOX4, and AKT1, promoting tumor invasion and metastasis." (PMID 38233930, 2024). "Collectively, our study not only indicates that NAT10 has an oncogenic role in LN metastasis of HNSCC and remodeling of the tumor microenvironment, but also suggests it as a potential therapeutic target for the novel treatment of HNSCC." (PMID 37914704, 2023). "N4-acetocytidine (ac4C) was an acetylation chemical modification of mRNA, and NAT10 is reported to regulate ac4C modification and enhance endoplasmic reticulum stress (ERS) in tumor metastasis." (PMID 36765042, 2023). "This study identified HSP90AA1 as a downstream target of NAT10-mediated mRNA ac4C modification in the regulation of HCC metastasis and ERS-related tumor resistance." (PMID 36765042, 2023). "NAT10 promoted CRC cell proliferation, migration and invasion, as well as tumor formation and metastasis by inhibiting ferroptosis through ac4C modification and stabilization of the ferroptosis suppressor protein 1 (FSP1) transcript." (PMID 37612540, 2023). "NAT10, CCT3, PLEK2, HOXB7, FOXD1, SEC61G, and so on have been identified as tumor markers in HNSCC by performing TCGA HNSCC database analysis." (PMID 37679666, 2023). "Here, we report a novel mechanism by which NAT10-mediated mRNA ac4C-modified HSP90AA1 regulates metastasis and tumor resistance in ERS of HCC." (PMID 36765042, 2023). "In our research, NAT10 was found to be highly expressed in BLCA and to participate in promoting tumour proliferation, metastasis and stemness maintenance by virtue of ac4C modification on binding target transcripts." (PMID 35522942, 2022). "Taken together, we explored the mechanism underlying NAT10-mediated ac4C modification in regulating CRC progression and observed that NAT10 could acetylate KIF23 mRNA, resulting in the activation of the Wnt/β-catenin pathway and leading to tumor proliferation and metastasis." (PMID 36522719, 2022). "Low survival probability was found in patients with high expression of NAT10, age ≥ 65, stage III and IV disease, HPV-negative status and recurrent tumours." (PMID 34362389, 2021). "NAT10 inhibitor has an anti-tumor effect in AML, which reveal the potential therapeutic impact of NAT10 inhibitor in AML." (PMID 33425753, 2020). "The present study provides experimental evidences that NAT10 is overexpressed in HCC and that NAT10 level is positively correlated with tumor stage." (PMID 28859621, 2017). "N-acetyltransferase 10 (NAT10), the primary writer of N4-acetylcytidine (ac4C) on RNA, is broadly upregulated across multiple cancer types and correlates with tumor proliferation, invasion, therapeutic resistance, and poor prognosis, indicating its significant clinical relevance." (PMID 41869016, 2026). "Immunohistochemical staining of NSCLC tissue sections further confirmed this observation, showing significantly higher NAT10 levels in tumor tissues than in surrounding non-tumor cells." (PMID 41310903, 2025). "Using a subcutaneous transplantation tumor model with NAT10-knockdown PANC-1 cells and NAT10-overexpressing MIA PaCa-2 cells, we observed that NAT10 knockdown significantly reduced tumor growth and weight, whereas NAT10 overexpression markedly enhanced tumor growth." (PMID 41203621, 2025). "Similarly, NAT10 promotes metastasis in HNSCC by stabilizing GLMP mRNA in an ac4C-dependent manner and reshaping the tumor microenvironment through the MAPK/ERK signaling pathway." (PMID 41446042, 2025).
tumor (continued). "Overall, NAT10 catalyzes ac4C deposition on its target mRNAs, enhancing their stability and translation efficiency to regulate downstream protein synthesis, leading to EMT transition and tumor metastasis." (PMID 40588654, 2025). "Transwell assays showed that NAT10 KD using siRNA or shRNA could significantly attenuate tumor migration and invasion in PANC-1 and MIA PaCa-2 cells, indicating that NAT10 promotes PDAC migration and invasion in vitro." (PMID 40119353, 2025). "Third, the broader RNA network regulated by NAT10 in the TME remains incompletely understood, as it may also influence other immune-related genes or signaling pathways that modulate tumor immunity." (PMID 41203621, 2025). "NAT10 plays a crucial role in regulating EMT and cancer metastasis in tumor cells." (PMID 39764566, 2025). "High NAT10/ac4C maintains mRNA stability, up-regulates FSP1, and accelerates tumor growth." (PMID 41446042, 2025). "Abnormal NAT10 expression patterns may also support angiogenesis in PDAC by activating the TGF‐β pathway, which contributes to distal tumor metastasis." (PMID 39817252, 2025). "NAT10 also upregulates JunB expression by increasing ac4C modification levels on its mRNA, which further upregulates LDHA expression and facilitated glycolysis and the immunosuppressive properties of tumor-infiltrating regulatory T cells." (PMID 40588654, 2025). "In addition to promoting primary tumor growth, NAT10 is a master regulator of epithelial-mesenchymal transition (EMT) and the subsequent multistep process of tumor metastasis." (PMID 41316475, 2025). "N-acetyltransferase 10 (NAT10)-ankyrin repeat and zinc finger peptidyl tRNA hydrolase 1 (ANKZF1) axis promotes tumor progression and lymphangiogenesis of ccRCC by enhancing the nuclear import of Yes1-associated transcriptional regulator (YAP1), and upregulating expression of VEGF-C/-D." (PMID 41511312, 2025). "Notably, NAT10 suppresses CD8+ T cell recruitment and cytotoxicity through the CCL25/CCR9 axis, fostering an immunosuppressive microenvironment that exacerbates tumor progression." (PMID 39648231, 2024). "Notably, NAT10 promoted proliferation, invasion, and metastasis in NSCLC cell lines, patient‐derived organoids, and xenograft tumor models." (PMID 38826095, 2024). "Transwell migration assays showed that NAT10 knockdown markedly reduced CD8+ T cell migration toward CRPC cells in co-culture, suggesting that NAT10 limits CD8+ T cell recruitment and cytotoxicity in the tumor microenvironment." (PMID 39648231, 2024). "The results showed that the expression intensity of NAT10 was significantly higher in LNM-positive tumor tissues than in LNM-negative tumors and corresponding non-tumor specimens." (PMID 37914704, 2023). "However, our study highlights the role of NAT10 in metastasis and tumor resistance in HCC under ERS and reveals the therapeutic potential of NAT10 in HCC." (PMID 36765042, 2023). "Furthermore, in the Clinical Proteomic Tumor Analysis (CPTAC) data portal, as expected, the protein level of NAT10 was higher in patients with an advanced clinical stage than in those with low clinical stage." (PMID 37914704, 2023). "Our data elucidate the oncogenic and drug-resistant role of NAT10 in HCC and highlight the importance of ac4C modification as a novel gene epigenetic regulatory pathway in tumor development, providing new insights into further mechanisms of tumorigenesis and progression." (PMID 36765042, 2023). "Further, an exploration of the relationship between NAT10 protein level and the clinicopathological characteristics of patients with CRC showed that tumor stage, lymph node metastasis, vascular invasion, and distant metastasis were statistically significantly associated with NAT10 expression." (PMID 36522719, 2022). "In addition, we examined the protein level of NAT10 using a commercial BLCA tissue microarray that included 16 pairs of tumour sections with adjacent normal tissues and 47 other tumour sections." (PMID 35522942, 2022).
tumor (continued). "Immunohistochemistry (IHC) in this regard showed up-regulated NAT10 expression in CRC tissues, as reflected by the higher degrees of staining and the H-scores obtained, consistent with Clinical Proteomic Tumor Analysis Consortium (CPTAC) data." (PMID 36522719, 2022). "Thus, we observed higher KIF23 mRNA levels in tumor tissues as well as a positive correlation between KIF23 mRNA expression and NAT10, consistent with TCGA or GEO datasets (GSE40967)." (PMID 36522719, 2022). "IHC staining were performed to detect the expression of NAT10 and Ki-67 in tumours from patients, the PDX model without Remodelin administration, and the PDX model with Remodelin administration." (PMID 34362389, 2021). "Fourteen of 19 (73.7%) tumor samples showed increased NAT10 protein levels compared with their respective paired noncancerous tissue." (PMID 28859621, 2017). "Furthermore, Remodelin combined with anti–PD-1 treatment substantially increased the infiltration of CD8+ T cells into the tumor, accompanied by a high percentage of GzmB+ and IFN-γ+ CD8+ T cells, demonstrating that NAT10 inhibition enhances the effects of PD-1 blockade." (PMID 41542770, 2026). "However, the inhibitory effect of Nat10 ablation on MC38 tumor growth was markedly greater in immunocompetent C57BL/6 mice than in immunodeficient BALB/c nude mice, as reflected by reduced tumor volume and weight." (PMID 41542770, 2026). "Here, we engineered NP1192, a PROTAC degrader targeting NAT10.NP1192 achieved nearly 70% NAT10 degradation and a 26.8% lower IC50 than canonical NAT10 inhibitor Remodelin in cervical cancercells, outperforming Remodelin in antitumor effect in vivo, in vitro, and across three tumor organoids." (PMID 41341045, 2025). "Moreover, the NAT10–ac4C–FOXP1 axis has been identified to augment lactic acid production and bolster glycolytic activity in CCa cells, thereby intensifying the immunosuppressive characteristics of tumor-infiltrating regulatory T cells." (PMID 39969189, 2025). "To test whether knockdown of NAT10 affects orthotopic tumor growth in vivo, we injected 231-BrM3 cells with or without NAT10 knockdown to the fourth mammary fat pads in mice." (PMID 40138393, 2025). "To further explore whether targeting the NAT10/XIST/YAP1 axis augments the antitumor effect of immune checkpoint inhibitors (ICIs), we administered Remodelin, Verteporfin, and an anti-PD-1 monoclonal antibody to tumor-bearing mice." (PMID 40860183, 2025). "Furthermore, NAT10 expression was significantly elevated in tumor tissues compared to neighboring non-cancerous tissues, according to qRT-PCR analysis of 138 pairs of NSCLC and adjacent normal tissue samples." (PMID 41310903, 2025). "NAT10 upregulates the transcription factor Forkhead box P1 (FOXP1) in CC to form the NAT10/ac4C/FOXP1 axis, which accelerates glycolytic metabolism, increases lactate production, and promotes immunosuppression in the tumor microenvironment by reprogramming glycolysis." (PMID 39640362, 2024). "Mechanically, it is up-regulated in tumor tissues and binds to NAT10, recruiting ubiquitin specific peptidase 39 (USP39) to block NAT10 ubiquitination-dependent degradation,thus promoting the formation of ac4C modification in mRNA, enhancing gene expression and leading to tumor occurrence." (PMID 38233930, 2024). "NAT10 was upregulated in HCC tumor tissues compared with non-tumorous liver tissues." (PMID 39085201, 2024). "The peritoneal dissemination assay showed that NAT10 knockout significantly reduced the formation of tumor nodules in the peritoneal cavity, and this effect could be reversed by the overexpression of wild-type NAT10 but not its mutant counterparts." (PMID 36609449, 2023). "Furthermore, NAT10 knockdown profoundly improved the efficacy of PD‐L1 blockade therapy by impairing tumor cell glycolysis, reducing lactic acid production, and enhancing immunosurveillance within the TME, ultimately resulting in tumor regression." (PMID 37818745, 2023).